INS (insulin)
Diseases named in the same sentence as INS in open-access papers (continued):
Sharing a sentence is not in itself a finding about the gene and the disease.
Hyperglycemia (continued). "In the present study, the effects of GOPs on hyperglycemia, insulin metabolism, oxidative stress, and expression of beta-cell apoptosis-related protein were evaluated for the first time." (PMID 28954411, 2017). "It is now well established that adipose tissue and skeletal muscle are main targets of insulin-stimulated glucose uptake to control of hyperglycemia." (PMID 28230764, 2017). "It was observed that the FDF45, FDF55 and NDF55 presented frank hyperglycaemia with significant (p <0.05) decrease in circulating serum insulin and C-peptides, a severe decrease which is classical of type 1 diabetes." (PMID 28129400, 2017). "Current treatments for hyperglycemia include oral hypoglycemic agents such as sulfonylureas and insulin secretagogues that stimulate insulin release from β-cells." (PMID 28788070, 2017). "These overall results implied that TRR has the ability to improve hyperglycemia possibly partly through insulin–pAkt–p-FOXO1 pathway or/and partly via AMPK activation to inhibit glucose production in liver tissues." (PMID 29099085, 2017). "For patients with insulin resistant status such as obesity and metabolic syndrome, partial agonist for adiponectin receptor is probably effective to suppress postprandial hyperglycemia." (PMID 29089472, 2017). "In conclusion, the hydroethanolic extract from S. sonchifolius leaves (HEYL) protects against hyperglycemia, oxidative stress, and inflammation in skeletal muscle and also promotes increase of serum insulin concentrations in STZ-induced diabetic model in rats." (PMID 28808475, 2017). "This promotes the uptake of free fatty acid into adipocytes, thus reducing ectopic fat deposition in skeletal muscle and liver, which is manifested as enhanced insulin sensitivity and reduced hyperglycaemia." (PMID 28112007, 2017). "Models such as the ZDF rat and the db/db mouse lose their beta cells very quickly once hyperglycemia develops leaving a very narrow window to look at mechanisms that center on beta cells and natural insulin release and function." (PMID 28640857, 2017). "The heterozygous mutation in the glucokinase-coding gene results in a changed insulin threshold and therefore persistent hyperglycemia." (PMID 28663157, 2017). "We claim that longer period of HFD feeding would lead to pancreatic beta cell failure, decrease in insulin levels towards a glucose stimulus, hyperglycemia and finally the establishment of T2DM." (PMID 29220408, 2017). "The 20% MBBP group showed a significant reduction in hyperglycemia and hyperinsulinemia; fasting blood glucose and insulin decreased from 25.0 to 14.8 mmol/L and 26.5 to 16.0 mU/L, respectively." (PMID 28970780, 2017). "For those who reported using insulin at Livongo program registration (n=1704), the likelihood of a day with hyperglycemia was decreased on average by 8.4% and the likelihood of hypoglycemia decreased by 12.5% in months 2-12 compared with month 1 (top)." (PMID 28698167, 2017). "DM is characterized by hyperglycemia resulting from defects in insulin secretion and/or insulin action." (PMID 28060743, 2017). "Once hypokalaemia is corrected and hydration commenced, insulin should be administered to halt lipolysis, ketogenesis, and correct hyperglycaemia." (PMID 28659865, 2017). "Adherence to the glibenclamide intervention was achieved in 9/13 (69.2%, 95%CI 38.6–90.9%) women, with 4 women switched to insulin therapy due to hyperglycaemia (n = 2) or hypoglycaemia (n = 2)." (PMID 28938877, 2017). "In fact, following intravenous injection of MSCs into diabetic mice, increases in insulin levels and reduced hyperglycaemia were observed." (PMID 28279194, 2017). "Hyperglycemia, which can result from insufficient insulin response, leads to long-term vascular damage and, in acute instances, can lead to life-threatening ketoacidosis." (PMID 28025655, 2017). "DM is characterized by persistent hyperglycaemia following disfunctions in insulin emission, insulin activity or both." (PMID 28045450, 2017).
Hyperglycemia (continued). "Many factors clarify hyperglycemia after dexamethasone administration, such as decreased insulin sensitivity, attenuated pancreatic α- and β-cell functions, and augmented hepatic gluconeogenesis." (PMID 29051443, 2017). "Metformin reduces hyperglycemia by increasing insulin sensitivity and reducing excessive hepatic gluconeogenesis." (PMID 28475161, 2017). "Defective insulin sensitivity in skeletal muscle and adipose tissues leads to hyperglycemia Insulin stimulated glucose uptake is accompanied with glut 4 transporters, predominantly distributed in muscles and adipose tissues." (PMID 28878669, 2017). "Focused on the usage of garlic, only one trial adopted a monotherapy of garlic compared with placebo, while all the other trials adopted a combination therapy compared with control (such as other hyperglycemia drugs or insulin)." (PMID 29056888, 2017). "In conclusion, we have shown that it is hard for trehalose to give rise to hyperglycemia and hypersecretions of insulin and GIP following ingestion." (PMID 28166771, 2017). "A previous study demonstrated that dietary intake of kaempferol significantly reduced hyperglycemia, hyperinsulinemia, and the circulating lipid profile level, and thus improved peripheral insulin sensitivity in obese diabetic mice." (PMID 28505121, 2017). "Although exogenous insulin administration can correct hyperglycemia this treatment is insufficient to prevent long-term complications, such as neuropathy, retinopathy and nephropathy." (PMID 27905403, 2016). "Time spent in hyperglycemia was significantly shorter in sensor-augmented insulin pump-treated patients than with MDI or self-monitoring blood glucose." (PMID 28004007, 2016). "Once hyperglycemia becomes apparent, β-cell function progressively deteriorates: glucose-induced insulin secretion becomes further impaired and degranulation of β-cells becomes evident, often accompanied by a decrease in the number of β-cells." (PMID 27941667, 2016). "When administered to diabetic mice, T1D-MSCs and C-MSCs similarly and successfully reversed hyperglycemia, improved β-cell mass, increased insulin production, and modulated pancreatic cytokine production." (PMID 26781648, 2016). "It has been shown that hyperglycemia is proinflammatory and is normally restrained by the anti-inflammatory effect of insulin secreted in response to that stimulus." (PMID 27034691, 2016). "Bilirubin is a potent antioxidant to play an important role for maintaining insulin sensitivity and preventing hyperglycemia." (PMID 27367602, 2016). "In the present study, intraperitoneal injection of STZ induced severe hyperglycemia and reduced fasting plasma insulin levels in rats, accompanied by a significantly decrease in body weight gains." (PMID 26819084, 2016). "T2D is a bihormonal disorder and hyperglycemia occurs as a result of inappropriate secretion of both insulin and glucagon." (PMID 27117413, 2016). "Obesity-induced T2DM is characterized by a progressive development of insulin resistance in liver and peripheral tissues accompanied by a defective insulin secretion from pancreatic beta cells leading to overt hyperglycaemia." (PMID 27759061, 2016). "The hyperglycemia in alloxan-induced diabetic mice can be reversed through EGFand CNTF treatment due to the generation of insulin-producing cells." (PMID 27795842, 2016). "Of patients with pretransplant DM who had insulin therapy before operation, 100% required basal-bolus insulin to control hyperglycemia." (PMID 28031946, 2016). "It is a chronic metabolic disorder diagnosed by hyperglycemia either due inadequate insulin production (type-1) or because of mutual endurance to insulin secretion and action (type-2)." (PMID 27446162, 2016). "Taken together, these results support that PT supplementation contributes to improving hyperglycemia and insulin sensitivity by decreasing the plasma FFA concentration." (PMID 27869712, 2016).
Hyperglycemia (continued). "Insulin treatment twice a day significantly reduced hyperglycemia after the injection of the long-acting insulin analog." (PMID 28042580, 2016). "Regarding convenience of implants compared to insulin injections, it is more effective and time-saving to implant rats once to influence hyperglycemia, than to inject insulin subcutaneously once or twice a day." (PMID 27253523, 2016). "In a T1D animal model, acute insulin-induced hypoglycaemia potentiated the detrimental effects of chronic hyperglycaemia in cortical and hippocampal MITO: the increase in ROS levels and decrease antioxidant defences." (PMID 27240327, 2016). "High fixed nutrition rates raise a patients BG all else equal, resulting in the need for higher or maximum insulin rates to control hyperglycemia." (PMID 27025951, 2016). "REACT patients with hyperglycemia were taking metformin (31%; 24 of 78), sulfonamide urea (27%; 21 of 78), and/or insulin (54%; 42 of 78) for glucose control at the start of the study." (PMID 27287020, 2016). "Our study offers a guideline for avoiding hyperglycemia by means of timely glycemic measurement and insulin therapy instead of delayed recognition." (PMID 27367602, 2016). "Hypothetically, metformin is an alternative to insulin in the treatment of hyperglycemia during pregnancy." (PMID 27597988, 2016). "Parallel with hyperglycemia, serum insulin levels were significantly increased in GK rats compared to Wistar controls at week 7 and more profoundly at week 11 showing the presence of hyperinsulinemia in GK animals." (PMID 27496100, 2016). "Two out of four patients responded to MSC transplantation by reducing exogenous insulin requirement to control hyperglycemia for 1–2 years and one patient became insulin-independent for three months." (PMID 27905403, 2016). "It has been suggested that hyperglycemia is a marker of extensive myocardial damage and a consequence of excessive secretion of stress hormones that inhibit the action of insulin." (PMID 27484985, 2016). "There are several obvious underlying reasons to explain the reported detrimental effect of T2D in the PC including hyperglycaemia, dyslipidemia, microvascular disease and dysfunctional insulin signalling." (PMID 26744321, 2016). "One of the major challenges in developing a fully closed-loop artificial pancreas is that subjects will neglect to provide a meal-related insulin bolus (feedforward control), which often results in a period of post-meal hyperglycemia (high blood glucose)." (PMID 30740333, 2016). "Pulsatile hormone release from human and mouse islets is generated by hyperglycaemia with coinciding pulses of insulin and somatostatin that are synchronized in opposite phase to the glucagon pulses." (PMID 27044660, 2016). "Recent pilot studies have demonstrated that such "permissive hyperglycemia" effectively reduces the need for exogenous insulin administration." (PMID 27633987, 2016). "Dapagliflozin reduces hyperglycaemia independently of insulin secretion or action, and as such, has a low intrinsic propensity for hypoglycaemia." (PMID 26895767, 2016). "BGE at 200 mg/kg reduced hyperglycemia, increased the insulin/glucose ratio and improved islet architecture and β-cell function in STZ-treated mice." (PMID 26751692, 2016). "This fact is supported by other investigations indicated that the insulin-mimetic actions of vanadium reduces the insulin resistance of peripheral tissues, which improves glucose uptake and relieves hyperglycemia." (PMID 26459400, 2016). "Insulin is required for all patients with type 1 diabetes, and is also necessary for many patients with type 2 diabetes to treat hyperglycemia." (PMID 26983499, 2016). "During the first week of life, the patient developed hyperbilirubinemia with mildly elevated liver enzymes, hyperammonemia, and hyperglycaemia which required insulin." (PMID 26761945, 2016).
Hyperglycemia (continued). "A large effect of kSP on AUCIn, with a much smaller effect on AUCGl, suggests that pancreatic responsiveness is stimulated by faster gastric emptying, so that rapid insulin release (high AUCIn) prevents hyperglycemia, leading to low AUCGl." (PMID 27253712, 2016). "All patients had random hyperglycaemia (at 21.8 ± 3.9 mmol/L) on the first day of admission and received insulin infusion intravenously (5 U/per hour)." (PMID 26697503, 2016). "1βEPP immunization reduced body weight gain, protected KK-Ay mice from hyperglycemia, improved glucose tolerance and insulin sensitivity, and decreased the serum levels of free fatty acids, total cholesterol and triglyceride." (PMID 27152706, 2016). "Once the fetal pancreas commences to produce and secrete insulin in the second trimester, fetal hyperglycaemia will result in fetal hyperinsulinemia and stimulation of fetal metabolism." (PMID 27645229, 2016). "The relative contribution of dysregulated glucagon secretion and impairment of insulin secretion to hyperglycaemia in diabetic patients has been a matter of debate." (PMID 27053237, 2016). "Approximately 50% of women with GDM go on insulin regimen, which requires close monitoring and intensive follow-up for regular insulin titrations to control persisting hyperglycemia." (PMID 27507708, 2016). "Attenuated actions of insulin result in hyperglycemia, decreased protein synthesis, increased protein degradation, and increased susceptibility to infection." (PMID 27069678, 2016). "Other renal parameters, like creatinine clearance and albuminuria appear elevated in STZ-treated rats after 26 days of hyperglycemia and were attenuated in rats supplemented with insulin implants." (PMID 27253523, 2016). "The pharmacological interventions to control hyperglycaemia include oral therapy with anti-diabetic agents and intramuscular administration of insulin." (PMID 28042834, 2016). "Diabetic db/db mice are characterized by hyperglycemia, lower pancreatic insulin stores, and higher plasma insulin levels resulting in pancreatic β-cell necrosis and atrophy." (PMID 27941667, 2016). "Both repaglinide and nateglinide belong to a class of glinides, which are Su-like agents that stimulate insulin secretion but are rapidly absorbed, with a short duration of action, thus contributing to reducing postprandial hyperglycemia." (PMID 26872083, 2016). "Interpretation of this clinical data has led to a large emphasis on the role of hyperglycemia in DN, however another interpretation of this data reveals that strict glycemic control also means a more balanced, steady, and physiological insulin exposure." (PMID 28066166, 2016). "Serum insulin levels were also raised (hyperinsulinaemia) at 5 months but were similar to WT levels at 8 months, despite continued hyperglycaemia." (PMID 27138913, 2016). "Studies from the literature have shown that chronic treatment with T3 attenuates hyperglycemia and improves insulin sensitivity in db/db mice, which are obese and hyperglycemic." (PMID 27655796, 2016). "Two-month oral vanadium therapy in STZ-diabetic rats ameliorated hyperglycemia by partially restoring plasma insulin." (PMID 26459400, 2016). "We investigated the effects of sustained vs. pulsatile hyperglycaemia in insulin resistant rats on markers of oxidative stress, enzyme expression and glucose metabolism in liver and aorta." (PMID 26790104, 2016). "These SC-β cells are characterized to express mature β cells markers and to showCa2+ flux after glucose challenge, insulin packaging, secretion of a considerable amount of insulin, and alleviation of hyperglycemia after its transplantation in diabetic mice." (PMID 26907255, 2016). "Both experimentally and in the model simulations, insulin resistant livers are unable to store sufficient glycogen, leading to post-prandial hyperglycaemia." (PMID 27632189, 2016).
Hyperglycemia (continued). "Human diabetic patients display elevated hepatic TSC22D4 expression, which correlates with decreased insulin sensitivity, hyperglycaemia and LCN13 serum levels." (PMID 27827363, 2016). "DM is a kind of metabolic diseases in which a person has hyperglycemia and decline in insulin secretion as common manifestations, either because of decline in β-cell function, or loss of response of cells to insulin." (PMID 27721485, 2016). "In this manuscript, we report that only specific hepatic IRA expression by AAV8 in iLIRKO mice is able to decrease the hyperglycaemia and plasma insulin levels, reverting the diabetic phenotype of these animals." (PMID 27562101, 2016). "A recent study showed a positive correlation between increased MDA in plasma and vascular dysfunction during hyperglycaemia both in insulin resistant and diabetic patients." (PMID 26790104, 2016). "In cases of hyperglycemia, glucose level can directly or indirectly, by inducing insulin release, influence cardiac autonomic modulations." (PMID 27441373, 2016). "Our previous studies demonstrated that β-cell-specific Mafk transgenic (Mafk-Tg) mice exhibited hyperglycemia due to an impaired insulin secretion during early postnatal life." (PMID 26901059, 2016). "Type 1 Diabetes (T1D) is characterized by the autoimmune destruction of pancreatic beta-cells and the need for insulin therapy to control hyperglycemia." (PMID 27755557, 2016). "The glulisine and aspart insulin also had their safety and efficacy demonstrated in controlling postprandial hyperglycemia in patients with DM2 and severe renal failure." (PMID 27471550, 2016). "Increased demand for insulin engendered by hyperglycaemia eventually leads to pancreatic β cell exhaustion, insulin deficiency and frank diabetes." (PMID 26467985, 2016). "When the cells become insulin resistant due to HFD the body is subjected to increased levels of hyperglycemia and lipotoxicity because of the excessive lipolysis." (PMID 27547764, 2016). "One of the therapeutic approaches to restoration of insulin sensitivity is to decrease postprandial hyperglycemia by retarding the absorption of glucose by inhibition of carbohydrate-hydrolyzing enzyme, such as α-glucosidase." (PMID 28035984, 2016). "Abnormal mitochondrial β-oxidation leads to hypertriglyceridemia, and excessive triglyceride accumulation in muscle and liver tissue, while pancreatic β-cell dysfunction results in hyperglycemia due to insufficient insulin production." (PMID 27070153, 2016). "Different strategies have been adopted over the years to help maintaining glucose homeostasis, thus avoiding disturbances in insulin metabolism and hyperglycaemia-related complications in type 2 diabetic individuals." (PMID 28042834, 2016). "Previous studies have shown that suppression of NADPH oxidase activity or protein expression can markedly decrease hyperglycemia induced ROS production in pancreatic beta cells and improve insulin secretion function." (PMID 26819084, 2016). "It is known that maternal hyperglycemia increases fetal insulin, which stimulates growth, and therefore offspring of mothers with gestational diabetes have higher birth weights." (PMID 26859631, 2016). "The pathogenesis of type 2 diabetes is complex and in most instances clearly requires defects in both β cell function and insulin sensitivity, and together both of these abnormalities bring about hyperglycemia." (PMID 27034691, 2016). "MODY patients typically present with hyperglycemia and impaired glucose-stimulated insulin secretion (GSIS) by young adulthood, while having normal body weight and lacking β-cell autoimmunity." (PMID 27185732, 2016). "In conclusion, procyanidins, especially cinnamtannin A2, significantly ameliorate postprandial hyperglycemia at least in part by promoting GLUT4 translocation to the plasma membrane by activating both insulin- and AMPK-signaling pathways." (PMID 27598258, 2016).